MITF (melanocyte inducing transcription factor)
Diseases named in the same sentence as MITF in open-access papers (continued):
Sharing a sentence is not in itself a finding about the gene and the disease.
melanoma (continued). "Agnarsdottir and colleagues showed that patients with melanomas where 25–75% of tumor cells stained with weak intensity for MITF expression using an anti-MITF antibody were at higher risk of death than patients with an overall strong MITF staining intensity." (PMID 24062982, 2013). "More recently, rare SNPs variants in MITF have been reported in melanoma and appear to act via naevi." (PMID 23796690, 2013). "Microphthalmia-associated transcription factor (MITF) is essential for melanocyte development and for the survival of both melanocytes and melanoma cells." (PMID 23480510, 2013). "The central role in the melanoma transcriptional network has the transcription factor MITF (microphthalmia-associated transcription factor)." (PMID 23349796, 2013). "According to the postulated rheostat model for MITF levels in melanoma cells, small changes of MITF level can cause very different cellular effects." (PMID 23349796, 2013). "MITF (microphthalmia-associated transcription factor), the master regulator of melanocyte proliferation, survival and differentiation, has intricate regulatory roles in melanoma development." (PMID 24039954, 2013). "Recently, a germinal mutation in the master gene of melanocyte homeostasis, microphthalmia-associated transcription factor (MITF), has been identified and shown to increase the risk of developing melanoma." (PMID 24416617, 2013). "Increased PGC-1α expression has recently been implicated in the etiology of a subset of human melanomas as a result of its induction by the melanocyte-specific transcription factor, MITF." (PMID 24350057, 2013). "Expression of MITF was also observed; this gene encodes a transcription factor that has a key role in melanoma cells by regulating cell cycle progression, survival, differentiation and invasion, and also modulates the expression of several pigmentation genes." (PMID 22532856, 2012). "MITF is also of clinical significance, as MITF mutations in humans cause Waardenburg syndrome type II, and a significant number of malignant melanomas harbour MITF amplifications." (PMID 22316093, 2012). "With a focus on developing potential therapies toward melanoma, both MITF and STAT3 have been implicated in neoplastic progression." (PMID 22316093, 2012). "The second class (B) prevalently expressed genes associated with melanoma signaling including MITF, melanoma differentiation antigens, and displayed a Th1 immune phenotype associated with better prognosis and likelihood to respond to immunotherapy." (PMID 22537248, 2012). "Recently, it was demonstrated that BHLHB2 mediated HIF-1α-induced microphthalmia-associated transcription factor (MITF) suppression, which causes increased metastasis in melanoma cells." (PMID 22973269, 2012). "The development of melanoma from a single melanocyte has been linked to a master regulator gene, the microphthalmia-associated transcription factor (MITF)." (PMID 22848417, 2012). "The overall expression of MITF in melanoma is associated with clinical outcome, however, melanomas are heterogeneous, appearing to contain individual cells with different phenotypic and gene expression patterns." (PMID 22536322, 2012). "For example, p16INK4 inactivation and BRAF mutation can accompany MITF amplification in melanoma cell lines, and ectopic MITF expression appears to work in synergy with BRAF mutation to transform primary human melanocytes." (PMID 22536322, 2012). "Since high levels of MITF are associated with differentiation and complete loss of MITF causes apoptosis, both up- or downregulation of MITF can have desirable effects for melanoma treatment, as long as the change in MITF levels is drastic enough." (PMID 22927992, 2012).
melanoma (continued). "Given that both MITF and SOX10 are frequently mutated in melanoma and that MITF itself is considered to be a lineage addiction oncogene, understanding the melanocyte GRN is of crucial importance." (PMID 21909283, 2011). "First, amplification of the chromosome 3p region covering MITF is considered as a typical driver mutation in melanoma." (PMID 22051105, 2011). "Microphthalmia-associated transcription factor (MITF) is believed to be one of the master molecules to regulate melanomagenesis among the many previously reported melanoma-associated molecules." (PMID 22046555, 2011). "Initially, we assessed changes in MITF expression in six human melanoma lines harboring oncogenic mutations in BRAF or NRAS, and in which ATF2 expression was effectively inhibited by corresponding shRNA (shATF2)." (PMID 21203491, 2010). "We found that reconstitution of BRG1 in a BRG1 deficient melanoma cell line promoted expression of MITF target genes that regulate melanogenesis and survival." (PMID 20969766, 2010). "Our quest to understand mechanisms underlying ATF2 activity in this process led us to identify an important role for ATF2 regulation of MITF, an important regulator of melanocyte biogenesis and a factor implicated in melanoma progression." (PMID 21203491, 2010). "Significantly, a high nuclear ATF2/MITF ratio in primary melanoma specimens was associated with decreased 10-year disease-specific survival (P = 0.0014)." (PMID 21203491, 2010). "As seen in earlier analysis, inhibition of ATF2 expression caused increase in MITF transcription in the human melanocytes and 4 melanoma cell lines, (WM1361, WM793, LU1205, WM35)." (PMID 21203491, 2010). "Several genes involved in the development of melanoma, including microphthalmia-associated transcription factor (MITF), c-Kit, V-raf murine sarcoma viral oncogene homolog B1 (BRAF) and neuroblastoma RAS viral oncogene homolog (N-RAS)." (PMID 24281076, 2010). "MiTF is a transcription factor required for melanocyte lineage survival and melanin production; MiTF is also implicated in melanoma progression and metastasis." (PMID 20174581, 2010). "In this regard, low levels of MITF protein were found in invasive melanoma cells and have been associated with poor prognosis and clinical disease progression." (PMID 19828018, 2009). "This is consistent with the work of other investigators that showed reduced levels of MITF was associated with increased invasiveness in melanoma cells, whereas MITF over-expression suppressed melanoma metastasis in mouse xenograft tumours." (PMID 20041153, 2009). "CDK2 and p21Cip1 are previously identified MITF target genes in melanoma cells and our data suggest that the melanoma susceptibility gene CDK4 is also an MITF target gene." (PMID 18628967, 2008). "For instance, SNP array analysis of a set of cancer cell lines has lead to the identification of the microphthalmia-associated transcription factor MITF as a melanoma oncogene." (PMID 18221515, 2008). "We show that BRAF depletion caused a substantial decrease in the activity of the MITF promoter in melanoma cells." (PMID 18628967, 2008). "Another protein that is important in melanoma is the basic helix-loop-helix leucine zipper transcription factor MITF (microphthalmia-associated transcription factor)." (PMID 18628967, 2008). "In agreement with this, low levels of MITF protein are found in invasive melanoma cells and are associated with poor prognosis and disease progression in patients." (PMID 18628967, 2008). "Another strategy appears to be gene amplification, since the MITF gene is amplified in approximately 15% of melanoma cases in which BRAF is mutated." (PMID 18628967, 2008). "In melanoma cells high levels of MITF expression are associated with the proliferative state in presence of an active differentiation program, whereas low MITF expression is associated with an invasive, undifferentiated state characterized by reduced proliferative capacity." (PMID 41596686, 2026).
melanoma (continued). "The microphthalmia-associated transcription factor (MITF) is a master regulator of melanocyte development and controls many aspects of melanocyte and melanoma biology, including the cell cycle, metabolism, DNA damage repair, survival, differentiation, and proliferation." (PMID 40809945, 2025). "Furthermore, Microphthalmia-associated transcription factor (MITF), a crucial regulator of melanoma metabolism and differentiation, was upregulated, resulting in enhanced melanogenesis and cell cycle arrest." (PMID 41422056, 2025). "In this respect, the influence of IFN-γ on melanoma-specific regulators of the dynamic plasticity of the cell phenotype, including microphthalmia-associated transcription factor (MITF) and nerve growth factor receptor (NGFR)/CD271 can affect the clinical efficacy of ICIs." (PMID 40108693, 2025). "In BRAF-mutant melanomas, the microphthalmia-associated transcription factor (MITF) positively regulates the expression of miR-579-3p, which in turn downregulates BRAF, stabilizes MITF protein, and induces its own transcription in a positive feedback regulatory loop." (PMID 39805813, 2025). "The miR-137, a proven tumor suppressor in melanomas and gliomas, is downregulated in lactotroph PitNETs, especially in invasive prolactinomas, as it acts as an inhibitor of microphthalmia-associated transcription factor (MITF) and is involved in cell differentiation, proliferation, and survival." (PMID 40362297, 2025). "MITF is also a transcriptional master regulator of an array of genes implicated in melanoma." (PMID 40141086, 2025). "Moreover, we also revealed that DAPL1 exists in a positive feedback loop with microphthalmia-associated transcription factor (MITF), which is a critical regulator of melanocyte development and acts as a tumor suppressor in melanoma." (PMID 38980592, 2025). "Both germline and somatic MITF mutations are associated with melanoma." (PMID 39092608, 2024). "In this paper, we report about the discovery of a novel mechanism controlling BRAF-mutated melanoma progression which involves the interplay between the well-known microphthalmia-associated transcription factor (MITF) and the recently discovered oncosuppressive miR-579-3p." (PMID 38472212, 2024). "Moreover, TNFα from THP1 macrophages induced expression of the transcription factor MITF in melanoma cells, which was associated with a decrease in BRAFi/MEKi-induced cell death." (PMID 38942020, 2024). "Assuming that classifications of primary melanoma by gene expression are biologically relevant and clinically useful, why do they all seem to converge on the function of microphthalmia-associated transcription factor (MITF), which is closely linked to plasticity or stemness of melanoma cells?" (PMID 38539487, 2024). "The microphthalmia-associated transcription factor MITF has been widely reported to be the master regulator of melanocyte biology in addition to being one of the key factors that is essential for the regulation of melanoma progression and invasion." (PMID 38275910, 2024). "Moreover, we verified the level of another protein, key during melanoma progression - microphthalmia-associated transcription factor (MITF)." (PMID 39175042, 2024). "Indeed, decreased expression of MITF and a concomitant increase in stem factors have been associated with resistance to treatment in melanoma." (PMID 39136013, 2024). "Interestingly, low MITF levels are also found in drug resistant melanoma cell lines, which was previously defined as hallmark of dormancy." (PMID 38419052, 2024).
melanoma (continued). "Given the impact of p300 activity on melanoma growth, direct regulation of MITF transcription by p300, and the concomitant loss of SOX10 and MITF protein expression following p300 inhibition in melanoma cells, we sought to further clarify the connection between SOX10, MITF, and p300." (PMID 38994683, 2024). "Additionally, the transcription factor NRF2, which is the major mediator of oxidative stress responses and linked to therapy resistance, suppresses MITF activity and reduces the expression of pigmentation markers in melanoma." (PMID 38790661, 2024). "In addition, some melanomas have low microphthalmia-associated transcription factor (MITF) expression." (PMID 38835341, 2024). "Although phenotypic diversity and plasticity in melanoma have been described >40 years ago, the molecular characterization of specific phenotypic states was first determined after the functional characterization of the gene encoding MITF." (PMID 38275910, 2024). "For example, a common BRAF mutation observed in melanoma (V600E) regulates oxidative metabolism through peroxisome proliferator-activated receptor–gamma coactivator 1-α (PGC1α) and MITF, linking increased mitochondrial capacity and resistance to oxidative stress." (PMID 39519202, 2024). "First, we examined the MITF gene (Microphthalmia-associated transcription factor), which plays a crucial role in regulating gene expression and has been associated with cancer development, such as melanoma." (PMID 39062480, 2024). "MITF is a known moderate risk gene for adult-onset melanoma." (PMID 37507557, 2023). "For example, Nrf2 inhibits the MITF (microphthalmia-associated transcription factor), the primary transcriptional regulator of the phenotypic transition in melanoma, and its expression changes through the melanoma progression." (PMID 36747120, 2023). "Melanoma plasticity consists of two distinct phenotypic states that co-exist in the tumor niche, the proliferative and the invasive, respectively associated with a high and low expression of MITF, the master regulator of melanocyte lineage." (PMID 37898636, 2023). "MITF amplification is seen in 15% to 20% of melanomas and is linked to a poor prognosis." (PMID 36980194, 2023). "In agreement, high MITF levels are associated with increased SNV burden in melanoma." (PMID 37131595, 2023). "In addition to Sox2, microphthalmia-associated transcription factor (MITF) is a marker of melanoma cell differentiation." (PMID 37614365, 2023). "MITF (microphthalmia-associated transcription factor) is one of the key molecular factors that regulate the differentiation, survival, and proliferation of both normal melanocytes and melanoma cells." (PMID 37371034, 2023). "Taken together, our data suggest that patients with immunotherapy-refractory melanoma could benefit from an acute therapy-induced decrease of MITF levels to increase their susceptibility to cytotoxic T cells." (PMID 36812891, 2023). "Conversely, MITF restoration in cultured melanoma cells causes T cell resistance." (PMID 36812891, 2023). "The authors suggested that the presence of MITF mutations might contribute to the resistance of NRAS-mutant melanomas to targeted therapies." (PMID 37504268, 2023). "Moreover, melanoma with low MITF expression is associated with resistance to BRAF inhibition therapy due to reactivation of ERK in the MAPK pathway." (PMID 37239381, 2023). "Resveratrol exposure induced differentiation in canine oral mucosal melanoma cells, enhancing their sensitivity to cisplatin and increasing the mRNA expression of melanoma differentiation markers, such as microphthalmia-associated transcription factor (MITF)." (PMID 38136176, 2023).
melanoma (continued). "Moreover, 10-HDA decreased the tyrosinase activity, along with the production of melanogenic enzymes, by inhibiting the microphthalmia-associated transcription factor (MITF) protein expression in B16F10 melanoma cells." (PMID 36771175, 2023). "Loss of SOX10 in melanoma cells results in cell cycle arrest in the G1 phase, accompanied by molecular changes such as reduced MITF expression, elevated p21/WAF1 and p27KIP2 expression, hypo-phosphorylated RB, and reduced levels of E2F1; SOX10 is essential for melanogenesis." (PMID 38132479, 2023). "There are several examples of MITF (microphthalmia-associated transcription factor) variants that have been studied in relation to the risk of melanoma development, a possible new useful marker for the selection of appropriate treatment or as a target for therapy." (PMID 37504268, 2023). "In some cases, MITF mutations have been observed in melanomas that also harbor BRAF mutations." (PMID 37504268, 2023). "Alternatively, this model can easily be pictured as a bell curve plot where low levels of MITF are associated with a G1 arrested or slow-cycling state of melanoma cells, and simultaneously possess high levels of the p27 cyclin-dependent kinase inhibitor, leading to invasiveness." (PMID 36675114, 2023). "The co-existence of microphthalmia-associated transcription factor (MITF) MITFhigh and MITFlow subpopulations in different regions of patient tumor samples was found, and the interaction between them was observed in a zebrafish melanoma xenograft model." (PMID 37370604, 2023). "The microphthalmia-associated transcription factor (MITF) pathway may also be involved in melanoma cell proliferation." (PMID 37658191, 2023). "Some melanosome-related proteins have been correlated with melanoma chemoresistance, for example the microphthalmia-associated transcription factor (MITF) was expressed at significantly higher levels in dacarbazine/temozolomide-resistant tumors when compared to sensitive tumors." (PMID 35495622, 2022). "Importantly, endogenous BRAF/MITF complexes were also detected in BRAF-mutated human melanoma cells." (PMID 35091687, 2022). "ARAF/MITF complexes were found in the cytosol of NRAS-mutated mouse melanoma cells." (PMID 35091687, 2022). "MITF has been previously implicated in melanoma survival pathways, suggesting that the suppression of MITF gene expression could explain the defective cell growth observed in DUSP4 knockdown cells." (PMID 35580987, 2022). "Moreover, melanoma profiles associated with low levels of MITF activity were enriched for genes directly inhibited by TFAP2." (PMID 35580127, 2022). "Altogether, mutations in these genes, associated with CDK4, TERT promoter, and MITF, are found in < 3% of melanoma-prone families in studied populations, and the majority (>70%) of familial cases are of unknown etiology." (PMID 35085295, 2022). "Increased activation of the WNT/MITF pathways is associated with proliferative melanoma." (PMID 35406524, 2022). "MITF (Microphthalmia-associated transcription factor) is the master regulator transcription factor in melanoma involved in the regulation of melanogenesis, as well as cell proliferation and survival by regulating several genes implicated in differentiation, survival, and metabolism." (PMID 35406721, 2022). "Indeed, MITF knockdown in melanoma cells leads to a senescent-like phenotype that is associated with NFkB (nuclear factor kappa-light-chain-enhancer of activated B cell) activation and production of an inflammatory secretome (CCL2, IL6, IL1)." (PMID 35682684, 2022).